KIF15 (kinesin family member 15)
Diseases named in the same sentence as KIF15 in open-access papers (continued):
Sharing a sentence is not in itself a finding about the gene and the disease.
tumor (continued). "In conclusion, PSMD12 could activated MEK-ERK pathway via KIF15 upregulation, thereby promoting tumor progression." (PMID 36137220, 2022). "In addition, downregulating the expression of KIF15 also decreased the migration and invasion of tumor cells." (PMID 36137220, 2022). "KIF15 knockdown impaired tumor progression and tumor-promoting effect of PSMD12." (PMID 36137220, 2022). "Firstly, tumor and normal tissues were collected for detecting expression of KIF15 in BL." (PMID 33985517, 2021). "Results of tumor weight measurement and in vivo bioluminescence imaging showed that down-regulation expression of KIF15 could inhibit the development of GC in mice (P < 0.01)." (PMID 32322172, 2020). "Consistently, a higher level of KIF15 was examined in tumor tissues." (PMID 32549756, 2020). "In addition, KIF15 might also have affected the classical PI3K/Akt signaling to promote tumor growth." (PMID 38433242, 2024). "Besides, KIF15 was also demonstrated to be connected with tumor stem cell properties, KIF15-silencing suppressed transcription and translation of stemness-related markers and drastically inhibited spheroid formation as well as growth of HCC patient-derived three-dimensional organoids in vitro." (PMID 38433242, 2024). "Additionally, it was observed that B7-H3 and KIF15 expression increased with tumor stage." (PMID 33011740, 2020). "KIF15 RNA and protein expression were found to be higher in LUAD and LUSC tumour tissues compared to normal tissues based on mining gene expression databases, IHC, and immunoblotting." (PMID 40002279, 2025). "Subsequent rescue experiments demonstrated that KIF15 overexpression reduced the anti-tumor efficacy of ATR-I against AR+ and AR− CRPC cells, indicating that ATR-I suppressed the CRPC progression through targeting KIF15." (PMID 40087774, 2025). "KIF15 up-regulation increased the expression of PHGDH, with the effects of eliminating ROS accumulation and facilitating stem cell phenotype and tumor development." (PMID 38433242, 2024). "Furthermore, several other kinesin inhibitors, such as KIF15-IN-1 (a synergistic inhibitor of Eg5) targeting KIF15, produces an effective suppression on tumor growth by combining with Eg5 inhibitors, which may be expected to overcome chemo-resistance during ispinesib monotherapy." (PMID 38433242, 2024). "For example, KIF3A and KIF13A are essential for cancer cell migration, a Kinesin13 family member MCAK leads to tumor invasion and paclitaxel resistance, and KIF20A and KIF15 contribute to the castration and Enzalutamide resistance of prostate cancer." (PMID 37711200, 2023). "We successfully explored the role of KIF15 in NPC; however, further functional experiments are still needed to clarify its effect on tumor biological process in vivo and in vitro." (PMID 35359374, 2022). "All 6 KIFs selected by LASSO regression were seen overexpressed in tumor samples comparing to normal samples (KIF10, KIF15, KIF18B, KIF4A: P < 0.0001; KIF18A: P = 0.0003; KIF20A: P = 0.0022), which in accordance with bioinformatics results." (PMID 32322170, 2020). "In summary, CDCA5, FOXM1, KIF15, MCM2, and ZWINT was involved in cell mitosis and supported our research results by affecting the cell cycle regulation of tumor pathogenesis." (PMID 31708970, 2019). "Additionally, the anti-tumor activity of ATR-I was diminished after KIF15 overexpression in AR+ and AR− CRPC cells, indicating that KIF15 expedited CRPC progression in both an AR-dependent- and independent manners, such as the EGFR signaling pathway." (PMID 40087774, 2025). "When KIF11 is absent, KIF15 (another member of the kinesin superfamily) can construct a complete bipolar spindle, leading to the proliferation of tumor cells that escape repression from the KIF11 inhibitors." (PMID 38672404, 2024).
tumor (continued). "Moreover, IHC analysis showed that knockdown of PSMD12 decreased the expression of KI67 in tumor tissue, and the p-ERK and KIF15 index of the PSMD12 knockdown group was also lower than that of the NC group, which is consistent with our previous study." (PMID 36137220, 2022). "The expression pattern and functional roles of KIF15 in tumor pathogenesis, especially in NPC, have not been comprehensively investigated." (PMID 35359374, 2022). "In addition, we found that PSMD12 can activate the MEK-ERK signaling pathway by upregulating the expression of KIF15, which is the molecular mechanism by which PSMD12 promotes the malignant progression of tumor cells." (PMID 36137220, 2022). "According to the IHC analysis, the expression of the KIF15 in the tumor tissues of BL was significantly higher than that of the normal tissues (P < 0.001)." (PMID 33985517, 2021). "Moreover, the lack of effect on spindle elongation after EG5 inhibition cannot be explained by activity of another plus-end-directed motor, KIF15, which acts redundantly with EG5 in control of spindle length during metaphase in human tumor cell lines." (PMID 33910056, 2021). "To address whether inhibiting KIF15 activity could reverse B7-H3-mediated CRC cell radioresistance in vivo, we performed a subcutaneous xenograft tumor assay using B7-H3-HCT116 and respective control cells in athymic nude mice." (PMID 33011740, 2020). "Furthermore, SW480-derived microvesicles are enriched with CENPE, KIF15, CEP55, CCNA2, NEK2, PBK, and CDK8 that are M-phase-related transcripts involved in tumorigenesis and tumor progression." (PMID 19930720, 2009). "However, in AR negative CRPC cells, KIF15 may promote tumor cell proliferation through activating EGFR signaling pathway." (PMID 34804913, 2021).
cancer (37 papers, 2014 to 2026). A tumor composed of atypical neoplastic, often pleomorphic cells that invade other tissues. "KIF15 was found to be positively associated with cell cycle, DNA damage, DNA repair, and proliferation in multiple cancer types." (PMID 35359374, 2022). "In the present study, we comprehensively analyzed the expression signature, prognostic value, and associated pathways of KIF15 across 33 types of human cancers using multiple databases." (PMID 35359374, 2022). "Similar to B7-H3, we find that the protein expression levels of KIF15, which showed a positive correlation with B7-H3, was abnormal upregulated in cancer tissues than in adjacent normal tissues and associated with TNM stage." (PMID 33011740, 2020). "Kinesin family member 15 (KIF15), a microtubule‐associated motor protein, mediates mitotic spindle dynamics and chromosome segregation, and its dysregulation has been increasingly implicated in cancer progression." (PMID 41584727, 2026). "Furthermore, some Kinesin family members, like KIF2C, KIF20A, KIF18A, and KIF15, have been linked to cancer progression and potentially to resistance against hormone-based therapies." (PMID 40869915, 2025). "Therefore, this study aimed to conduct a pan-cancer analysis of KIF15 and evaluate its diagnostic and prognostic potential in NPC." (PMID 35359374, 2022). "Several studies showed that KIF15 is associated with cancer progression and tumorigenesis." (PMID 36280663, 2022). "Notably, the results indicated that HNSC, KIRC, LGG, LIHC, PRAD, and THYM were six cancer types most strongly associated with KIF15 expression in immune cell infiltrating level, including B cells, CD8+ T cells, CD4+ T cells, macrophages, neutrophils, and dendritic cells." (PMID 35359374, 2022). "All these results indicated that cell cycle pathway plays crucial roles in KIF15-mediated growth promotion and provided the potential that KIF15 silencing synergizes with cell cycle inhibitor to produce more significant anti-cancer effect in GBM treatment." (PMID 39430242, 2024). "Although the expression of KIFC1 did not significantly differ between MP and BP cell lines, KIFC1 can serve as a target to promote KIF11/KIF15-dependent centrosome declustering in BP cancer cells." (PMID 39074902, 2024). "KIF15 is a kind of driver protein, and its abnormal expression is closely related to the occurrence and development of malignant tumors." (PMID 37658042, 2023). "Meanwhile, the transcriptionally active AR induced KIF15 expression, which generated a positive feedback system that promotes drug resistance and cancer progression." (PMID 36807568, 2023). "Some research groups have reported that the abnormal expression of KIF15 is related to the occurrence and development of a variety of malignancies." (PMID 37658042, 2023). "Aberrant expression of KIF15 promotes cancer cell proliferation and migration and inhibits cell apoptosis." (PMID 36807568, 2023). "We performed immunohistochemical analysis of ACAT2, SPHK1, SNED1, KPNA2, BZW2 and KIF15 in cancer and normal tissues and statistically analyzed the staining intensity." (PMID 37202800, 2023). "KIF15 plays a vital role in many biological processes and has been reported to influence the occurrence and development of certain human cancers." (PMID 35359374, 2022). "Regarding the key functional role of KIF15 in cancers, we detected the expression level of KIF15 in NPC tissue through the GEO datasets and IHC." (PMID 35359374, 2022). "We further explored the mechanism of KIF15 promotion of FA disassembly by accelerating endosome trafficking to enhance cancer cell migration." (PMID 36280663, 2022). "KIF15 is a novel tumorigenic protein involved in the regulation of cancer cell biological functions." (PMID 36137220, 2022). "We suspect that a high neoantigens load led to the dysregulation of KIF15, and thus affected the development of cancer." (PMID 35359374, 2022).
cancer (continued). "The increased expression level of KIF15 was correlated with worse clinical outcomes in many types of human cancers." (PMID 35359374, 2022). "KEGG and GO enrichment analysis were carried out to explore the potential functions of KIF15 in cancer." (PMID 35359374, 2022). "In the analysis of CancerSEA database, the functional state of KIF15 was explored at the single-cell level in 14 types of cancer." (PMID 35359374, 2022). "The expression of KIF15 was significantly upregulated in 20 out of 33 cancer types compared to adjacent normal tissue." (PMID 35359374, 2022). "has shown that over-expression of KIF15 promoted the cancer stem cell (CSC) phenotype and malignancy through phosphoglycerate dehydrogenase (PHGDH)-regulated intracellular reactive oxygen species disorders in HCC." (PMID 35359374, 2022). "According to our findings, KIF15 was highly related to IDO1 expression in 11 out of 33 cancer types." (PMID 35359374, 2022). "Based on KM and univariate analyses, it was found that high expression of KIF15 indicated poor survival in several cancers, including OS, DFI, DSS, and PFI." (PMID 35359374, 2022). "Together, higher expression levels of KIF15 represented an unfavorable prognostic indicator in pan-cancer." (PMID 35359374, 2022). "In the present study, it was found that KIF15 was closely related to the expression of LAG3 in 16 out of 33 cancer types." (PMID 35359374, 2022). "Previous studies have indicated that KIF15 plays a vital role in the disease progression of most cancers." (PMID 35359374, 2022). "The ability of KIF15 knockdown to inhibit the growth of BL cell has prompted us to explore the expression of some classical signaling pathways in cancer." (PMID 33985517, 2021). "Dihydropyrazole and dihydropyrrole structures-based design of KIF15 inhibitors are considered as new therapeutic agents for cancer." (PMID 32549756, 2020). "KIF15 is a tetrameric spindle motor which can regulate mitosis in cellular process and exert the crucial functions in several cancers." (PMID 32549756, 2020). "Kinesin family member 15 (KIF15) plays an important role in many malignant tumors with a tetrameric spindle motor structure." (PMID 33117795, 2020). "Although the interaction between GSG2 and KIF15 has been elucidated, their synergistic functions in bladder basically low spontaneous apoptosis of T24 cells cancer still needed to be investigated." (PMID 32439830, 2020). "To further investigate the correlations between B7-H3 and KIF15 protein levels, we analyzed 123 cancer tissues and adjacent normal tissues of patients with CRC by IHC staining." (PMID 33011740, 2020). "The results showed that the protein expression levels of both B7-H3 and KIF15 were much higher in cancer tissues than in adjacent normal tissues." (PMID 33011740, 2020). "Among these genes, CDCA5, FOXM1, KIF15, MCM2, and ZWINT were the most reported genes associated with cancer progression, including EOC." (PMID 31708970, 2019). "Hence, dual inhibition of KIF11 and the KIF15/TPX2 axis is essential to disrupt the mitotic activity of cancer cells." (PMID 37894278, 2023). "The interaction between KIF15 and DUBs was also confirmed in other cancers." (PMID 36807568, 2023). "Given that KIF15 is a member of the kinesin family, involved in the transportation of cancer related proteins, we speculate that KIF15 regulated the metabolic reprogramming of PC cells by interacting with other regulators." (PMID 36807568, 2023). "Therefore, the relationship between KIF15 expression and immune cell infiltration in pan-cancer was explored." (PMID 35359374, 2022). "In summary, these integrated analyses suggest that high expression of KIF15 may serve as a poor prognostic biomarker in most cancers." (PMID 35359374, 2022). "Despite the limitation of our study, we conclude that KIF15 could be a promising prognostic biomarker in pan-cancer as well as in NPC." (PMID 35359374, 2022).
cancer (continued). "Our findings revealed the important and functional role of KIF15 as an oncogene in pan-cancer." (PMID 35359374, 2022). "The results of our pan-cancer analysis revealed that KIF15 expression was significantly upregulated in most type of cancers, suggesting that KIF15 might act as an oncogene in pan-cancers." (PMID 35359374, 2022). "The results of our study could contribute to a better understanding of the effects of KIF15 on cancer (specifically NPC) occurrence, development, and prognosis." (PMID 35359374, 2022). "A meta-analysis was performed to further clarify the prognostic value of KIF15 in cancers." (PMID 35359374, 2022). "In this study, KIF15 significantly related to CTLA4 expression in 17 out of 33 cancer types." (PMID 35359374, 2022). "However, the effects of KIF15 in cancer immunity and cancer microenvironment have been seldomly reported, and further investigation is urgently needed to clarify its role in cancer." (PMID 35359374, 2022). "Moreover, we selected several common immune genes and examined their correlation with KIF15 expression levels in various cancer types." (PMID 35359374, 2022). "Kyoto Encyclopedia of Genes and Genomes enrichment (KEGG) analysis showed that KIF15 could participate in several cancer-related pathways." (PMID 35359374, 2022). "Additionally, based on the GEPIA platform, higher mRNA expression levels of KIF15 also indicated a worse prognostic outcome in pan-cancer." (PMID 35359374, 2022). "Abundant evidence reported that KIF15 was involved in the progression of human cancer." (PMID 33985517, 2021). "KIF15 expression in those cancers was extremely high and it accelerated cancer progression." (PMID 32549756, 2020). "The functions of KIF15 in human cancers were also investigated to some extent." (PMID 32439830, 2020). "KIF15 is a tetrameric spindle motor which exert the crucial functions in several cancers." (PMID 32549756, 2020). "KIF15 is a gene involved in immune diseases and cancer progression." (PMID 32848739, 2020). "Kinesin family member 15 (KIF15) is overexpressed in various cancers." (PMID 32322172, 2020). "Scientists hope, therefore, that a better understanding of the role of Kif15 may lead to improved cancer treatments." (PMID 24668168, 2014). "However, the functions of KIF15 in pan-cancer are not fully understood." (PMID 35359374, 2022). "Moreover, correlation between KIF15 and immune gene set was analyzed, and the expression of several important immune-related genes was significantly related to KIF15 expression level in pan-cancer, such as CTLA4, IDO1, and LAG3." (PMID 35359374, 2022). "Moreover, it has been reported that KIF15 could assist cancer cells to develop chemotherapy resistance, thus affecting the efficiency of cancer treatment." (PMID 32322172, 2020). "For instance, KIF15 interacted with phosphoglycerate dehydrogenase (PHGDH) and stabilized it, thus promoting cancer stem cell phenotype and malignancy via PHGDH-mediated reactive oxygen species imbalance in HCC." (PMID 37957153, 2023). "Further investigation of BIRC5, H2AFZ, HIST1H2BK, KIF15, UBE2S, and FBXO5 is crucial to broaden the understanding of cancer invasion and migration, and to promote the discovery and evaluation of new therapeutic targets." (PMID 35406376, 2022). "Thus, KIF15 might serve as novel cancer therapeutic targets." (PMID 35359374, 2022). "The five genes (FANCB, KIF15, KIF4A, ERCC6L, and UBE2C) are all involved in fundamental cellular functions and found in many types of cancers." (PMID 32703154, 2020). "Given its synergistic effects on both cancer cells and the TME, targeting KIF15 may represent a novel combinatorial strategy to overcome immunotherapy resistance, particularly in immune “cold” tumors." (PMID 41584727, 2026). "KIF11, KIF15, and KIF23 are overexpressed in several cancer types." (PMID 32642733, 2020). "However, abnormal overexpression of KIF15 and NCAPG2 has been detected in many other types of cancer." (PMID 32582275, 2020).
cancer (continued). "Finally, B7-H3/KIF15 enhanced resistance against irradiation in CRC cells via activating ERK1/2 signaling, a key pathway involved in radioresistance in cancer." (PMID 33011740, 2020). "Drugs that interfere with Kif11 have been developed in the hope that they will stop cancer cells dividing, but these drugs have not been very effective in clinical tests, possibly due to the Kif15 back up." (PMID 24668168, 2014).
infection (3 papers, 2017 to 2023). The state of being infected such as from the introduction of a foreign agent such as serum, vaccine, antigenic substance or organism. "The data suggest that Kif15 recruits EspW to the site of bacterial attachment, which in turn activates Rac1, resulting in modifications of the actin cytoskeleton that are essential to maintain cell shape during infection." (PMID 28630074, 2017). "No change in FoxO6 and Kif15 expression was found in non‐CMs following Ang‐II treatment, regardless of infection with the FoxO6 adenovirus (Ad)." (PMID 37799807, 2023). "The exact role of Kif15 during infection is still unclear, as labeling of EspW in EPEC did not allow us to localize the effector during infection." (PMID 28630074, 2017).
immune diseases (2 papers, 2018 to 2020). "KIF15 also inhibits the endocytic trafficking of α2 integrin, implicated in various immune diseases." (PMID 30670970, 2018).
adenocarcinoma (1 paper, 2020). A common cancer characterized by the presence of malignant glandular cells. "Similarly, most of GC are adenocarcinomas, thus the expression level of KIF15 may also be used to assess postoperative survival in patients with GC." (PMID 32322172, 2020).
KIF15 also shares sentences with these, for which no sentence is quoted: Burkitt lymphoma (2 papers); oral cancer (2); triple-negative breast carcinoma (2); acute myeloid leukemia (1); anaplastic oligodendroglioma (1); breast tumors (1); colon cancer (1); gallbladder cancer (1); leukemia (1); lymphoma (1); meningioma (1); multiple myeloma (1); neuroblastoma (1); ovarian cancer (1); Pan (1); rhabdomyosarcoma (1); skin cancer (1); synovial sarcoma (1); testicular cancer (1); uterine cancer (1).